SLC27A5 (solute carrier family 27 member 5)
Description:
May mediate the import of long-chain fatty acids (LCFA) by facilitating their transport across cell membranes. Also catalyzes the ATP-dependent formation of fatty acyl-CoA using LCFA and very-long-chain fatty acids (VLCFA) as substrates. Mainly functions as a bile acyl-CoA synthetase catalyzing the activation of bile acids via ATP-dependent formation of bile acid CoA thioesters which is necessary for their subsequent conjugation with glycine or taurine. Both primary bile acids (cholic acid and chenodeoxycholic acid) and secondary bile acids (deoxycholic acid and lithocholic acid) are the principal substrates. In vitro, activates 3-alpha,7-alpha,12-alpha-trihydroxy-5-beta-cholestanate ((25R)-3alpha,7alpha,12alpha-trihydroxy-5beta-cholestan-26-oate or THCA), the C27 precursor of cholic acid deriving from the de novo synthesis from cholesterol. Plays an important role in hepatic fatty acid uptake and bile acid reconjugation and recycling but not in de novo synthesis of bile acids (By similarity).
Synonyms: FATP-5; BAL; BACS; VLCS-H2; VLCSH2; VLACSR; ACSB; ACSVL6; FACVL3; FATP5; FLJ22987
Tractability: Antibody: UniProt places it where antibodies can reach, with medium confidence; UniProt predicts a signal peptide or a membrane-spanning region; its Gene Ontology location is reachable by antibodies, with medium confidence.
Target class: Electrochemical transporter; Transporter; SLC27 family of fatty acid transporters; SLC superfamily of solute carriers
Gene: Protein-coding gene on chromosome 19 (58,479,512 to 58,512,413, reverse strand). Ensembl gene ENSG00000083807.
Subcellular location: Endoplasmic reticulum membrane; Microsome; Cell membrane
Pathways (Reactome):
Metabolism: Recycling of bile acids and salts; Synthesis of bile acids and bile salts via 24-hydroxycholesterol; Synthesis of bile acids and bile salts via 7alpha-hydroxycholesterol
Gene Ontology:
Molecular function: cholate-CoA ligase activity; long-chain fatty acid transmembrane transporter activity; protein binding; very long-chain fatty acid-CoA ligase activity; long-chain fatty acid-CoA ligase activity; fatty acid transmembrane transporter activity; protein-containing complex binding
Biological process: bile acid biosynthetic process; very long-chain fatty acid metabolic process; bile acid and bile salt transport; bile acid metabolic process; long-chain fatty acid import into cell; long-chain fatty acid metabolic process; fatty acid metabolic process; long-chain fatty acid transport
Cellular component: endoplasmic reticulum; endoplasmic reticulum membrane; plasma membrane; basal plasma membrane; protein-containing complex
Genetic constraint (gnomAD): Loss-of-function variants: 49 observed, 59.08 expected, observed/expected ratio (o/e) 0.83, 90% interval 0.66 to 1.05. The upper end of that interval is the gene's LOEUF score, 1.05, which puts it in group 4 of 6, group 1 being the genes least tolerant of losing a copy. Missense variants: 940 observed, 889.99 expected, observed/expected ratio (o/e) 1.06, 90% interval 1 to 1.12. Synonymous variants: 391 observed, 383.04 expected, observed/expected ratio (o/e) 1.02, 90% interval 0.94 to 1.11.
Homologues: Orthologues: chimpanzee SLC27A5 (99% identical), macaque SLC27A5 (94% identical), guinea pig SLC27A5 (76% identical), rabbit SLC27A5 (76% identical), rat Slc27a5 (72% identical), mouse Slc27a5 (71% identical), pig SLC27A5 (69% identical), dog ZBTB45 (62% identical), tropical clawed frog slc27a3 (39% identical), zebrafish zgc:158482 (39% identical), zebrafish slc27a2b (38% identical), Drosophila melanogaster Fatp3 (31% identical), and 25 more. Paralogues in human: SLC27A2 (41% identical), SLC27A3 (40% identical), SLC27A6 (39% identical), SLC27A4 (35% identical), SLC27A1 (35% identical), ACSL6 (19% identical), ACSL1 (18% identical), ACSL5 (17% identical), ACSL4 (17% identical), ACSL3 (17% identical), ACSBG1 (15% identical), ACSBG2 (14% identical).
Diseases named in the same sentence as SLC27A5 in open-access papers:
SLC27A5 is named in the same sentence as 57 diseases in open-access papers, as found by Europe PMC text mining. Sharing a sentence is not in itself a finding about the gene and the disease. The quoted sentences say what the papers report.
Hepatic steatosis (18 papers, 2012 to 2025). Steatosis is a term used to denote lipid accumulation within hepatocytes. "However, SR treatment attenuated HFD-induced hepatic steatosis by suppressing TG contents and the expression of fatty acid transport- and lipogenesis-related genes including Fabp1, Fabp4, Slc27a5, Pparg, Mlxipl, Srebf1, Srebf2, Fas, Dgat1, and Dgat2." (PMID 35454963, 2022).
hepatocellular carcinoma (14 papers, 2016 to 2025). A malignant tumor that arises from hepatocytes. "Deficiency of SLC27A5 promotes the progression of hepatocellular carcinoma (HCC) and is strongly associated with a poor prognosis." (PMID 40290127, 2025). "Solute carrier family 27 member 5, a key enzyme in fatty acid transport and bile acid metabolism in the liver, is frequently expressed in low quantities in patients with hepatocellular carcinoma, resulting in poor prognosis." (PMID 38059827, 2024). "Critically, SLC27A5 enhances the therapeutic efficacy of sorafenib in hepatocellular carcinoma by promoting sorafenib-induced ferroptosis through inhibition of the NRF2/GSR pathway." (PMID 39633985, 2024). "SLC27A5 suppresses proliferation and migration of hepatocellular carcinoma cells in vitro." (PMID 39633985, 2024). "Moreover, expression levels of SLC27A5 are significantly lower in patients with hepatocellular carcinoma." (PMID 39633985, 2024). "Since the low expression of SLC27A5 in sorafenib-resistant hepatoma cells, we sought to focus on analyzing whether SLC27A5 is functionally involved in sorafenib resistance." (PMID 36635256, 2023). "In addition, SLC27A5 is also a potential prognostic biomarker for hepatocellular carcinoma." (PMID 35203444, 2022).
liver cancer (6 papers, 2021 to 2025). An epithelial or non-epithelial malignant neoplasm that arises from the liver. "In vitro assays, SLC27A5 holds promise as a potential prognostic marker for liver cancer and IGF2 has been linked to unfavourable clinical outcomes." (PMID 39628446, 2024). "Particularly, several key genes, such as SLC27A5, IGF2, EFNA3, DCAF4L2, and SPP1, have been demonstrated to be associated with liver cancer." (PMID 39628446, 2024). "To further explore the role of SLC27A5 deletion in liver cancer metastasis, we performed RNA sequencing (RNA‐seq) on invasive liver cancer tissues in WT mice and Slc27a5−/‐ mice." (PMID 38059827, 2024). "To investigate the role of SLC27A5 in liver cancer, we overexpressed SLC27A5 in HepG2 and LM-3 cells." (PMID 38157255, 2023). "In order to observe the role of SLC27A5 in liver cancer metastasis, we restored the expression of SLC27A5 in invasive liver cancer via tail vein injection of AAV8‐TBG control and AAV8‐TBG‐Slc27a5 (n = 6) in WT or Slc27a5−/‐ mice." (PMID 38059827, 2024). "Taken together, these results indicate that SLC27A5 can suppress liver cancer progression by interacting with IGF2BP3, independent of its enzyme activity." (PMID 38059827, 2024).
dyslipidemia (4 papers, 2013 to 2023). "Studies have shown that Slc27a5 knockout mice have reduced FA intake, accompanied by liver injury, insulin resistance, and dyslipidemia." (PMID 38003277, 2023).
Cirrhosis (3 papers, 2021 to 2025). A chronic disorder of the liver in which liver tissue becomes scarred and is partially replaced by regenerative nodules and fibrotic tissue resulting in loss of liver function. "In our study, we observed that the expression of the bile acid‐CoA ligase SLC27A5 was decreased in patients with cirrhosis and fibrosis mouse models." (PMID 37957540, 2024). "Analyzing the cirrhosis dataset (GSE25097) revealed that the expression of SLC27A5 was negatively correlated with that of fibrosis‐related genes such as ACTA2, COL1A1, and COL3A1." (PMID 37957540, 2024). "This study demonstrates that solute carrier family 27 member 5 (SLC27A5), an enzyme involved in BAs metabolism, is substantially downregulated in the liver tissues of patients with cirrhosis and fibrosis mouse models." (PMID 37957540, 2024).
liver fibrosis (3 papers, 2020 to 2025). "The loss of SLC27A5 aggravates liver fibrosis induced by carbon tetrachloride (CCI4) and thioacetamide (TAA)." (PMID 37957540, 2024). "In summary, these results suggest that SLC27A5 deficiency in mice promotes liver fibrosis by inhibiting BAs conjugation." (PMID 37957540, 2024). "In conclusion, SLC27A5 deficiency in mice drives hepatic fibrosis through CA‐induced activation of HSCs, highlighting its significant implications for liver fibrosis treatment." (PMID 37957540, 2024). "Moreover, SLC27A5 deficiency aggravates the progression of liver fibrosis by activating hepatic stellate cells (HSCs) via the regulation of bile acid (BA) conjugation." (PMID 37957540, 2024). "Hence, we conclude that SLC27A5 deficiency promotes liver fibrosis progression by upregulating unconjugated CA levels." (PMID 37957540, 2024). "Furthermore, we noted that SLC27A5 deficiency promoted liver fibrosis." (PMID 37957540, 2024). "To further examine the role of SLC27A5 in liver fibrosis, we investigated fibrogenesis in Slc27a5−/− mice subjected to CCl4 and TAA treatment." (PMID 37957540, 2024). "We also observed a stepwise decrease in the level of SLC27A5 transcript from fibrosis stages 0 to 4 in a cohort of patients with hepatitis B virus (HBV)‐related liver fibrosis." (PMID 37957540, 2024). "The findings reveal that experimental SLC27A5 knockout (Slc27a5−/−) mice display spontaneous liver fibrosis after 24 months." (PMID 37957540, 2024). "We believe that our findings can provide mechanistic insights into the role of SLC27A5 in regulating liver fibrosis." (PMID 37957540, 2024). "Our findings demonstrate that the expression of SLC27A5 is diminished in the livers of cirrhotic patients and mice with liver fibrosis." (PMID 37957540, 2024). "To evaluate the role of SLC27A5 in the development of liver fibrosis, we analyzed SLC27A5 mRNA expression levels in normal and fibrotic liver biopsy samples from the Gene Expression Omnibus (GEO) database." (PMID 37957540, 2024). "In the present study, we have mainly focused on the role of SLC27A5 in regulation of BAs conjugation during the progression of liver fibrosis." (PMID 37957540, 2024). "Overall, these findings suggest that the re‐expression of SLC27A5 or inhibition of CA accumulation ameliorates the pathogenesis of liver fibrosis, providing a potential strategy for treating this condition." (PMID 37957540, 2024). "In the present study, we identified SLC27A5 as a novel regulator of liver fibrosis progression." (PMID 37957540, 2024). "Re‐expression of SLC27A5 or inhibition of CA levels could be a promising strategy for liver fibrosis treatment." (PMID 37957540, 2024). "Another important finding of this study was the physiological role of SLC27A5 in liver fibrosis." (PMID 37957540, 2024). "Notably, WT mice with SLC27A5 overexpression exhibited a mild alleviation of liver fibrosis compared with those injected with AAV‐Control." (PMID 37957540, 2024). "The re‐expression of hepatic SLC27A5 by an adeno‐associated virus or the reduction of CA levels in the liver using A4250, an apical sodium‐dependent bile acid transporter (ASBT) inhibitor, ameliorates liver fibrosis in Slc27a5−/− mice." (PMID 37957540, 2024). "Therefore, we aimed to elucidate the role of SLC27A5 in regulating BAs conjugation during the progression of liver fibrosis." (PMID 37957540, 2024). "To identify the putative transcription factors (TFs) responsible for the downregulation of SLC27A5 in liver fibrosis, we analyzed the potential promoter region of SLC27A5 using the JASPAR database considering the 2‐kb upstream sequence of the transcription start site of SLC27A5." (PMID 37957540, 2024). "We thus hypothesize that SLC27A5 overexpression might protect against liver fibrosis." (PMID 37957540, 2024). "Additionally, the injection of AAV‐Slc27a5 at an earlier time point may be a better choice to investigate the effects of SLC27A5 overexpression on the treatment of liver fibrosis." (PMID 37957540, 2024).
liver fibrosis (continued). "Furthermore, we monitored the effect of the lack of SLC27A5 in mice on the activation of HSCs and liver fibrosis and investigated the associated molecular mechanisms." (PMID 37957540, 2024). "Another study demonstrated that RUNX2 promotes liver fibrosis and HSC activation by increasing unconjugated cholic acid through binding the SLC27A5 promoter and downregulating SLC27A5." (PMID 40287769, 2025). "Consistently, human cirrhotic tissue samples and mouse models of liver fibrosis induced by carbon tetrachloride (CCI4) and thioacetamide (TAA) also revealed reduced SLC27A5 expression compared with that in the control trials." (PMID 37957540, 2024). "In liver fibrosis, RUNX2 has been reported to activate hepatic stellate cells (HSCs) by upregulating Itgav expression and functioning as a transcriptional inhibitor of SLC27A5, resulting in the buildup of cholic acid and subsequent activation of HSCs." (PMID 40287769, 2025). "However, other functions of SLC27A5, such as transportation of LCFA in liver fibrosis, need further investigation." (PMID 37957540, 2024).
lung carcinoma (3 papers, 2017 to 2024). "In addition, the specific roles of novel NRF2-targeted genes such as ABHD14B, LRP8, and SLC27A5 in lung cancer need to be investigated." (PMID 29050246, 2017).
melanoma (3 papers, 2024 to 2025). A malignant, usually aggressive tumor composed of atypical, neoplastic melanocytes. "The SLC27A5 promoter mutations were associated with increased SLC27A5 expression in melanoma tumors." (PMID 40359938, 2025). "We subsequently also verified SLC27A5 and CAMK4, in which we identified mutation clusters of interest in melanoma." (PMID 40359938, 2025). "The up-regulation of CPT1, ACSL3, SLC27A5, and associated PC content was primarily detected in SOX6 + C1/C2 melanoma cells, suggesting that fatty acid transport, rather than fatty acid oxidation, constitutes the primary mechanism in AM metastasis." (PMID 40866912, 2025).
glioblastoma (2 papers, 2023 to 2024). The most malignant astrocytic tumor (WHO grade IV). "Similarly to the analysis of all patients, male samples showed a positive correlation of SLC27A1 expression with SLC27A3, SLC27A4 with SLC27A5, SLC27A4 with SLC27A6, and SLC27A5 with SLC27A6 in the studied regions of the glioblastoma tumor." (PMID 37239243, 2023). "In glioblastoma tumors, specifically in the tumor core, women exhibit lower expression of SLC27A1 and SLC27A3, but higher expression of SLC27A5 than men." (PMID 37239243, 2023). "In female patients with glioblastoma, a positive correlation was found between the expression of SLC27A4, SLC27A5, and SLC27A6 and the number of cigarette packs smoked in their lifetime." (PMID 37239243, 2023). "In women, there was a positive correlation between the expression of SLC27A4, SLC27A5, and SLC27A6 with cigarette smoking in all investigated regions of the glioblastoma tumor and in the peritumoral area, whereas no such relationship was observed in men." (PMID 37239243, 2023).
Hyperglycemia (2 papers, 2015 to 2024). An increased concentration of glucose in the blood. "Mice with the hepatic Slc27a5 gene silenced showed that inhibiting the expression of FATP5 reversed NAFLD induced by a high-fat diet and improved hyperglycemia." (PMID 39850557, 2024).
esophageal cancer (1 paper, 2024). A primary or metastatic malignant neoplasm involving the esophagus. "However, the expressions of SLC27A5 and ALOXE3 were not significantly upregulated in esophageal cancer tissues compared to control tissues." (PMID 39633985, 2024).
Hepatitis B (1 paper, 2023). "For example, for Hepatitis B, predicted gene #2, F5; predicted gene #6, DECR1; predicted gene #7, SLC27A5, and predicted gene #9, DPP4, are all associated with liver function by the GeneCards platform." (PMID 36791052, 2023).
non-alcoholic fatty liver disease (1 paper, 2024). "SLC27A5, which is involved in fatty acid transport and bile acid transport, has been shown to be associated with methylation and influence the development of non-alcoholic fatty liver disease, and a high level of expression of these genes helps new pigs to metabolize fatty energy in colostrum." (PMID 39202427, 2024).
non-small cell lung carcinoma (1 paper, 2024). A group of at least three distinct histological types of lung cancer, including non-small cell squamous cell carcinoma, adenocarcinoma, and large cell carcinoma. "Knockout of SLC27A5 activates the KEAP1/NRF2 pathway, which is linked to chemoresistance in non-small cell lung cancer patients and different types of cancer cell lines." (PMID 38797968, 2024).
ovarian carcinoma (1 paper, 2024). A malignant neoplasm originating from the surface ovarian epithelium. "Reduced expression of SLC27A5 is closely associated with poorer OS in ovarian cancer patients." (PMID 39633985, 2024).